SH2B1 (SH2B adaptor protein 1)
Diseases named in the same sentence as SH2B1 in open-access papers (continued):
Sharing a sentence is not in itself a finding about the gene and the disease.
Obesity (continued). "The expression levels of other eight obesity-related genes (TMEM18, KCTD15, GNPDA2, SH2B1, FTO, LEP, PCSK1, and GPR120) in about half types of cancer tissues were higher/lower than those in the corresponding normal tissues." (PMID 33299884, 2020). "Concordance was now observed only for three phenotypes (inflammatory bowel disease, prostate cancer, obesity-related phenotypes) and a total of 3 genes (MST1, MSMB and SH2B1, respectively)." (PMID 21072174, 2010). "Ablation of Sh2b1 in PVHSH2B1 neurons induces BDNF resistance in the PVH, contributing to obesity." (PMID 38885417, 2024). "SH2B1 directly enhances BDNF signaling in PVHSH2B1 neurons, thereby increasing the ability of the PVHSH2B1→DRN neurocircuit to defend against energy imbalance, obesity, and metabolic disease." (PMID 38885417, 2024). "Mice lacking SH2B1 display severe obesity, elevated expression of AgRP/NPY, and impaired activation of JAK2 and STAT3." (PMID 38027481, 2023). "Hypothalamic Slug–elicited epigenetic reprogramming may act in concert with Sh2b1, SOCS3, PTP1b, and additional regulators to promote leptin resistance and obesity." (PMID 36512408, 2023). "Sh2b1ΔPOMC mice with POMC neuron-specific ablation of Sh2b1, unlike Sh2b1ΔLepR mice, did not develop obesity and insulin resistance." (PMID 32251290, 2020). "SNPs in SH2B1, SFRS10 and KCTD15 associated with increased risk of overweight, but not with obesity, while the risk alleles in MC4R and NEGR1 associated with increased risk of obesity, but not with overweight." (PMID 23861046, 2013). "We next built a prioritization score that weighs each of the eight methods based on whether or not they prioritized one or more of the six established obesity genes located in any of the 536 BMI-associated loci (i.e., LEPR, POMC, PCSK1, DGKI, SH2B1, and MC4R)." (PMID 38754426, 2024). "It is likely that Slug may have additional epigenetic targets involved in leptin resistance and obesity, such as positive regulators, like Sh2b1, and negative regulators, like SOCS3 and PTP1b, of LepRb signaling." (PMID 36512408, 2023). "Hence, some obesity-related genes (LEPR, NEGR1, TMEM18, and SH2B1) may play critical roles in preventing progression and metastasis of kidney cancer." (PMID 33299884, 2020). "The comparison of changes in the expression levels of obesity-related genes between the occurrence of cancer and patients' survival revealed four obesity-related genes (LEPR, NEGR1, TMEM18, and SH2B1), which might play critical roles in preventing the progression and metastasis of kidney cancer." (PMID 33299884, 2020). "Liver-specific deletion of SH2B1 also did not affect HFD-induced obesity in HKO mice." (PMID 24358267, 2013). "The obesity genes MC4R, FTO and SH2B1 may participate in the central control of energy homeostasis." (PMID 19878575, 2009).
Insulin resistance (22 papers, 2012 to 2025). Increased resistance towards insulin, that is, diminished effectiveness of insulin in reducing blood glucose levels. "This revealed that SH2B1-2/SEZ6L2-1 duplications are associated with reduced trunk fat despite higher insulin resistance, a paradoxical finding suggesting leptin pathway modulation." (PMID 40429924, 2025). "Another group also described SH2B1 mutations in extremely obese children with insulin resistance." (PMID 25955518, 2015). "MBH-specific overexpression of SH2B1 substantially ameliorated HFD-induced insulin resistance and glucose intolerance, as assessed by ITT, GTT, and insulin-stimulated phosphorylation of Akt." (PMID 32251290, 2020). "Like Sh2b1ΔLepR mice, adult-onset and MBH-specific Sh2b1 knockout mice developed hyperinsulinemia, glucose intolerance, and insulin resistance." (PMID 32251290, 2020). "Sh2b1 knockout mice are obese, hyperphagic and exhibit traits of the metabolic syndrome like hyperlipidemia, leptin resistance, hyperglycemia, and insulin resistance." (PMID 25955518, 2015). "We have reported that TgKO mice, which lack SH2B1 only in peripheral tissues, have normal body weight, but they are still predisposed to high fat diet (HFD)-induced insulin resistance and glucose intolerance." (PMID 24358267, 2013). "Since deletion of SH2B1 in the entire peripheral tissues exacerbates HFD-induced insulin resistance and glucose intolerance in TgKO mice, SH2B1 in other peripheral tissues (e.g. skeletal muscle and/or adipose tissue) is likely to promote insulin regulation of glucose metabolism." (PMID 24358267, 2013). "Surprisingly, hepatocyte-specific deletion of SH2B1 did not cause hyperinsulinemia, hyperglycemia, insulin resistance, or glucose intolerance in HKO mice." (PMID 24358267, 2013). "To determine whether hepatic SH2B1 is involved in HFD-induced insulin resistance, we fed HKO and control male mice a HFD." (PMID 24358267, 2013). "Deletion of Sh2b1 specifically in DRN‐projecting PVHSH2B1 neurons also resulted in glucose intolerance and insulin resistance, as assessed in GTT and ITT." (PMID 38885417, 2024). "Adult-onset deletion of hepatic SH2B1 also did not exacerbate HFD-induced insulin resistance and glucose intolerance in mice." (PMID 24358267, 2013). "Adult-onset deletion of SH2B1 in the liver either alone or in combination with whole body SH2B2 knockout also did not exacerbate HFD-induced insulin resistance and glucose intolerance." (PMID 24358267, 2013). "Furthermore, simultaneous deletion of both hepatic SH2B1 and whole body SH2B2 neither caused insulin resistance nor exacerbated HFD-induced insulin resistance and glucose intolerance." (PMID 24358267, 2013).
type 2 diabetes (11 papers, 2011 to 2024). "BDNF rs4923461 displayed a borderline BMI-dependent protective effect on type 2 diabetes (0.87 (0.78–0.96, p = 0.008)), whereas SH2B1 rs7498665 associated with nominally BMI-independent increased risk of type 2 diabetes (1.16 (1.07–1.27, p = 7.8×10−4))." (PMID 21912638, 2011). "SH2B1 rs7498665 associated with type 2 diabetes independently of BMI." (PMID 21912638, 2011). "Only the SH2B1 rs7498665 G-allele strongly associated with increased risk of type 2 diabetes when adjusting for age and sex with an allelic OR of 1.18 (1.09–1.28, p = 3.0×10−5) and when additionally adjusting for BMI a nominal association sustained with an OR of 1.16 (1.07–1.27, p = 7.8×10−4)." (PMID 21912638, 2011). "At the SH2B1 (rs7498665) locus, the AA genotype was most abundant in patients with overweight and type 2 diabetes (42.9%), and GG was most abundant in obese diabetic patients (24.4%)." (PMID 32228543, 2020). "The risk of type 2 diabetes has only been addressed in two other studies, and here association between TMEM18, GNPDA2, ETV5, FAIM2 and SH2B1 and a BMI-dependent increased risk of type 2 diabetes have been reported." (PMID 21912638, 2011). "Hence, we are the first to report a tendency towards an increased risk of type 2 diabetes independent of BMI for SH2B1, and rs7498665 could therefore be suggested as a type 2 diabetes variant if this association is replicated in other independent studies." (PMID 21912638, 2011). "After adjusting for sex and age, loci near TMEM18 (rs6548238) and FAIM2 (rs7138803), but not SH2B1 (rs7498665), near GNPDA2 (rs10938397), MTCH2 (rs10838738) and near MC4R (rs12970134), were associated with increased risk for type 2 diabetes in obese individuals." (PMID 32228543, 2020).
Glucose intolerance (7 papers, 2012 to 2024). Glucose intolerance (GI) can be defined as dysglycemia that comprises both prediabetes and diabetes. "In summary, we report that liver-specific deletion of SH2B1 does not affect hepatic glucose production, systemic insulin sensitivity, and glucose intolerance." (PMID 24358267, 2013).
colorectal cancer (6 papers, 2020 to 2025). A primary or metastatic malignant neoplasm that affects the colon or rectum. "For instance, SH2B1 exhibited higher expression in colorectal cancer, and this was correlated with the adverse prognosis." (PMID 41410190, 2025). "Here, we provide evidence to suggest that the BBOX1‐AS1/miR‐361‐3p/SH2B1 axis promotes colorectal cancer cell proliferation, migration, and invasion, and inhibits cell apoptosis." (PMID 31984680, 2022). "Moreover, hsa_circ_0136666 is highly expressed in CRC and the silence of hsa_circ_0136666 regulates the proliferation and migration of colorectal cancer (CRC) cells by sponging miR-136, thus modulating the expression of SH2B adaptor protein 1 (SH2B1)." (PMID 33520987, 2020).
developmental delay (5 papers, 2019 to 2024). "Microdeletions in the 16p11.2 region that include the SH2B1 gene have been implicated as risk factors for IUGR, congenital heart anomalies, dysmorphic features, and developmental delay, although with incomplete penetrance." (PMID 39202413, 2024). "Additionally, ARFGEF2, MIPEP, NONO, SH2B1, and TMEM70 led to LVNC complicating developmental delay." (PMID 34819141, 2021).
diabetes (5 papers, 2010 to 2024). "Given the previously reported strong association between SH2B1 and diabetes risk, we further controlled for diabetes diagnosis." (PMID 38434247, 2023). "Even after adjustment for diabetes diagnosis, the genetic associations between SH2B1 polymorphisms and FI remained significant in the UKBB sample." (PMID 38434247, 2023).
Hepatic steatosis (4 papers, 2013 to 2025). Steatosis is a term used to denote lipid accumulation within hepatocytes. "Hyperinsulinemia may counteract hepatic SH2B1-deficiency and stimulate lipogenesis and hepatic steatosis in TgKO mice." (PMID 24358267, 2013). "In animal studies, an association has been drawn between SH2B1 with an increasing hepatic lipid content and/or VLDL secretion, promoting hepatic steatosis in mice." (PMID 32365683, 2020). "Adult-onset deletion of liver SH2B1 similarly attenuated HFD-induced hepatic steatosis in SH2B2 KO mice 29 days after infection." (PMID 24358267, 2013). "Unlike embryonic deletion of hepatic SH2B1 in HKO mice, adult-onset deletion of hepatic SH2B1 attenuated HFD-induced hepatic steatosis in both SH2B1f/f and SH2B1f/f:SH2B2KO mice." (PMID 24358267, 2013). "Hepatic steatosis in TgKO mice may be explained by SH2B1 regulation of crosstalk between different metabolic tissues." (PMID 24358267, 2013). "Interestingly, deletion of SH2B1 in the entire peripheral tissues augmented HFD-induced hepatic steatosis in TgKO mice." (PMID 24358267, 2013). "Adult-onset, but not embryonic, deletion of SH2B1 in the liver attenuated HFD-induced hepatic steatosis." (PMID 24358267, 2013). "Adult onset, but not embryonic, deletion of hepatic SH2B1 attenuates HFD-induced hepatic steatosis." (PMID 24358267, 2013).
metabolic syndrome (4 papers, 2020 to 2024). A cluster of metabolic risk factors for CARDIOVASCULAR DISEASES and TYPE 2 DIABETES MELLITUS. "Higher blood pressure, which is also part of metabolic syndrome, was found in SH2B1 minor allele carriers." (PMID 36980961, 2023).
cardiac hypertrophy (3 papers, 2019 to 2025). "Although SH2B1 was detected as a direct target for miR-142-3p in cardiac hypertrophy, its role in miR-142-3p-induced mitochondrial protection is unclear." (PMID 31547607, 2019). "MiR-142-3p-attenuated cardiac hypertrophy is overexpressed by inhibiting the expression of Src homology 2 B adaptor protein 1 (SH2B1), a regulator of energy metabolism with a pro-hypertrophic role." (PMID 31547607, 2019). "SH2B1 silencing was documented to reduce glycolysis in a cardiac hypertrophy model." (PMID 41410190, 2025). "Moreover miR-142 was found to protect mitochondrial function and inhibit the expression of SH2B1 gene which directly leads to alleviation of cardiac hypertrophy." (PMID 38256030, 2024).
lung adenocarcinoma (3 papers, 2019 to 2025). A carcinoma that arises from the lung and is characterized by the presence of malignant glandular epithelial cells. "A previous study has implicated that SH2B1 is highly-expressed and linked with epithelial to mesenchymal transition biomarkers and poor prognosis in patients with lung adenocarcinoma, and SH2B1 has important roles on cell proliferation, migration, and invasion in A549 and H1299 cells." (PMID 31417870, 2019). "SH2B1 enhanced the EMT process in lung adenocarcinoma through the IRS1/β‐catenin axis." (PMID 31984680, 2022). "Besides, our previous study reported that SH2B1 could interact with insulin receptor substrate 1 (IRS1) to increase its expression, which facilitated epithelial–mesenchymal transition of lung adenocarcinoma cells." (PMID 41410190, 2025).
lung cancer (3 papers, 2021 to 2025). A malignant neoplasm involving the lung. "SH2B1 promoted cell proliferation in non‐small cell lung cancer via phosphoinositide 3‐kinase/Akt/mechanistic target of rapamycin signaling cascade." (PMID 31984680, 2022). "Besides, SH2B1 knockout led to downregulation of GLUT1, PDK1, and LDHA in lung cancer cells." (PMID 41410190, 2025). "Additionally, phosphoproteomic analysis of ALK-positive lung cancer cells with or without gilteritinib treatment revealed that gilteritinib significantly decreased phosphorylation of ALK and its adapter proteins such as IRS1/2, SOS2, or SH2B1." (PMID 33627640, 2021).
autism spectrum disorder (2 papers, 2019 to 2022). A spectrum of developmental disorders that includes autism, and Asperger syndrome. "Similarly, microduplication of 16p11.2 comprising ATXN2L, TUFM, SH2B1, and ATP2A1 genes can lead to the onset of microcephaly and autism spectrum disorder." (PMID 35722491, 2022).
hypogonadism (2 papers, 2024 to 2025). A disorder characterized by decreased function of the gonads. "NYNRIN, TUFM, and SH2B1 were uniquely identified by colocalization analysis of hypogonadism, while NF1, PABPC4, and SHROOM3 were uniquely identified through colocalization analysis of total testosterone." (PMID 40316537, 2025).
morbid obesity (2 papers, 2021 to 2022). An excess of body weight, normally defined as an individual with a body mass index greater than 35 or a body weight greater than one hundred percent of ideal body weight. "Deletion of chromosome 16p11.2, which SH2B adaptor protein 1 (SH2B1) locates nearby, causes morbid obesity." (PMID 33826123, 2022). "2, TUFM, SH2B1, ATP2A1-AS1, and RABEP2) located in the 16p11.2 region, SH2B1 was reported as the causal gene of morbid obesity." (PMID 34529725, 2021).
Anxiety (1 paper, 2023). Intense feelings of nervousness, tension, or panic often arise in response to interpersonal stresses. "Finally, we subjected Sh2b1+/+ and Sh2b1ΔN mice to behavioral paradigms assessing basal locomotor activity and anxiety, including the open field and elevated zero maze tests." (PMID 38434247, 2023). "Taken together, our results suggest that hippocampal Sh2B1 plays a specific role in working memory, short-term novel object recognition memory, and behavioral flexibility, while leaving general learning abilities, basal locomotor activity, and anxiety unaffected." (PMID 38434247, 2023).
autism (1 paper, 2019). Persistent deficits in social interaction and communication and interaction as well as a markedly restricted repertoire of activity and interest as well as repetitive patterns of behavior. "First, SH2B1 is located in 16p11.2, which is the one of the most common chromosomal abnormal regions in autism." (PMID 31379474, 2019). "In future study, CNV and RNA expression data should be further added in order to identify discrete SH2B1 showing methylation differences between autism and controls." (PMID 31379474, 2019).
Darier disease (1 paper, 2017). Darier disease (DD) is a keratinization disorder characterized by the development of keratotic papules in seborrheic areas and specific nail anomalies. "The genes disturbed by the CNVs mainly involve the SH2B1, TUFM, ATP2A1, and ATP2A2 genes, of which mutations of the single ATP2A2 gene in Darier disease have been found to be connected to the neuropsychiatric abnormalities frequently observed in Darier disease." (PMID 28680393, 2017).
endometrial carcinoma (1 paper, 2025). A malignant tumor arising from the epithelium that lines the cavity of the uterine body. "Moreover, SH2B1 was upregulated by circ_0075960 via sponging miR‐361‐3p, which facilitated endometrial carcinoma development." (PMID 41410190, 2025).
gastric cancer (1 paper, 2022). A primary or metastatic malignant neoplasm involving the stomach. "For example, SH2B1 was identified as a risk factor in gastric cancer and stimulated its progression." (PMID 31984680, 2022).
hepatic disease (1 paper, 2020). "Interestingly, the results yielded evidence that the SH2B1 has an impact on the development and progression of this hepatic disease." (PMID 32365683, 2020).
Infertility (1 paper, 2010). "Genetic deletion of SH2B1 in mice produces neonatal growth retardation and infertility probably due to impaired responses to GH or IGF-1." (PMID 20333234, 2010). "Genetic knockouts of SH2B1 in mice also show infertility due to impaired signal transduction from the IGF-1 receptor resulting in poor gonad development." (PMID 20333234, 2010).
kidney cancer (1 paper, 2020). Primary or metastatic malignant neoplasm involving the kidney. "Underexpressed LEPR, NEGR1, TMEM18, and SH2B1 genes prevented the progression and metastasis of kidney cancer." (PMID 33299884, 2020). "However, patients with kidney cancer in the high-expression level group for each of TMEM18 and SH2B1 genes had a long life expectancy than those who in the low/medium-expression level group." (PMID 33299884, 2020).
leukemia (1 paper, 2020). A malignant (clonal) hematologic disorder, involving hematopoietic stem cells and characterized by the presence of primitive or atypical myeloid or lymphoid cells in the bone marrow and the blood. "And we also find that the other two members [SH2B1 and APS (SH2B2)] of this family of proteins share similar sequence homologies in leukemia cells, whose stimulatory and inhibitory roles also appear to be cell-type and pathway dependent." (PMID 32322171, 2020).
lymph node metastasis (1 paper, 2016). "SH2B1 expression was positively correlated with TNM stage and lymph node metastasis of NSCLC (P < 0.001)." (PMID 27164951, 2016).
memory impairment (1 paper, 2023). "In humans, loss of function of BDNF and its receptor TrkB, as well as SH2B1 deficiency, have been associated with speech and language delay, behavioral abnormalities, and memory impairment, features overlapping the behavioral and cognitive phenotypes seen in deletion carriers." (PMID 37586323, 2023).
myocardial infarction (1 paper, 2022). Gross necrosis of the myocardium, as a result of interruption of the blood supply to the area, as in coronary thrombosis. "SH2B1 is also associated with myocardial infarction in diabetic patients while, Genome-Wide Association Studies (GWAS) have associated variants in SH2B1 with BMI." (PMID 36277770, 2022).
non-small cell lung carcinoma (1 paper, 2022). A group of at least three distinct histological types of lung cancer, including non-small cell squamous cell carcinoma, adenocarcinoma, and large cell carcinoma. "For instance, the low expression of miR-361-3p attenuates the proliferation and metastasis of non-small-cell lung cancer cells by inhibiting the SH2B1 gene." (PMID 36590309, 2022).
steatosis (1 paper, 2020). Increased lipid within the cytoplasm of cells. "At the same time, rs7359397_SH2B1 was associated with the steatosis degree, evidencing a higher risk of higher liver fat accumulation in subjects carrying the risk allele." (PMID 32365683, 2020). "The results of another article showed defects in the SH2B1 genetic variant in obese patients with diabetic problems, which are important risk factors for the development of steatosis." (PMID 32365683, 2020).